TERT (telomerase reverse transcriptase)
Description:
Telomerase is a ribonucleoprotein enzyme essential for the replication of chromosome termini in most eukaryotes. Active in progenitor and cancer cells. Inactive, or very low activity, in normal somatic cells. Catalytic component of the teleromerase holoenzyme complex whose main activity is the elongation of telomeres by acting as a reverse transcriptase that adds simple sequence repeats to chromosome ends by copying a template sequence within the RNA component of the enzyme. Catalyzes the RNA-dependent extension of 3'-chromosomal termini with the 6-nucleotide telomeric repeat unit, 5'-TTAGGG-3'. The catalytic cycle involves primer binding, primer extension and release of product once the template boundary has been reached or nascent product translocation followed by further extension. More active on substrates containing 2 or 3 telomeric repeats. Telomerase activity is regulated by a number of factors including telomerase complex-associated proteins, chaperones and polypeptide modifiers. Modulates Wnt signaling. Plays important roles in aging and antiapoptosis.
Synonyms: TP2; EST2; TCS1; TRT; hEST2; CMM9; DKCA2; DKCB4; PFBMFT1; hTRT
Tractability: Small molecule: a high-quality ligand is known; it belongs to a druggable protein family. Antibody: its Gene Ontology location is reachable by antibodies, with medium confidence. PROTAC: UniProt records ubiquitination sites on it; a small molecule that binds it is known. Other modalities: a drug acting on it is in phase 2 or 3 trials.
Target class: Enzyme; Transferase
Chemical probes: BIBR1532 (high quality), Braco-19
Gene: Protein-coding gene on chromosome 5 (1,253,147 to 1,295,085, reverse strand). Ensembl gene ENSG00000164362.
Subcellular location: Nucleus, nucleolus; Nucleus, nucleoplasm; Nucleus; Chromosome, telomere; Cytoplasm; Nucleus, PML body
Subcellular location (Human Protein Atlas): Nucleoplasm; Cytosol; Nuclear speckles
Pathways (Reactome):
Cell Cycle: Telomere Extension By Telomerase
Developmental Biology: Regulation of MITF-M-dependent genes involved in DNA replication, damage repair and senescence
Signal Transduction: Formation of the beta-catenin:TCF transactivating complex
Gene Ontology:
Molecular function: DNA binding; DNA polymerase activity; identical protein binding; protein binding; protein homodimerization activity; protein-folding chaperone binding; RNA binding; RNA-directed DNA polymerase activity; RNA-directed RNA polymerase activity; telomerase activity; telomerase RNA binding; template-free RNA nucleotidyltransferase; transcription coactivator binding; tRNA binding; telomeric DNA binding
Biological process: cellular response to hypoxia; DNA biosynthetic process; DNA strand elongation; establishment of protein localization to telomere; mitochondrion organization; negative regulation of cellular senescence; negative regulation of extrinsic apoptotic signaling pathway in absence of ligand; positive regulation of miRNA transcription; positive regulation of protein localization to nucleolus; positive regulation of Wnt signaling pathway; protein import into nucleus; regulation of protein stability; replicative senescence; RNA-templated DNA biosynthetic process; RNA-templated transcription; siRNA processing; siRNA transcription; telomere maintenance via telomerase; positive regulation of hair cycle; positive regulation of stem cell proliferation; telomere maintenance; telomere maintenance via recombination; heart development; negative regulation of apoptotic process; negative regulation of endothelial cell apoptotic process; and 7 more
Cellular component: chromosome, telomeric region; cytosol; mitochondrial nucleoid; nuclear speck; nucleolus; nucleoplasm; nucleus; PML body; RNA-directed RNA polymerase complex; telomerase catalytic core complex; telomerase holoenzyme complex; TERT-RMRP complex; nuclear telomere cap complex; cytoplasm; mitochondrion; plasma membrane
Genetic constraint (gnomAD): Loss-of-function variants: 41 observed, 89.67 expected, observed/expected ratio (o/e) 0.46, 90% interval 0.35 to 0.59. The synonymous counts are far from expectation, so gnomAD's model fits this gene poorly and the ratio says little. Missense variants: 1,101 observed, 1,416.5 expected, observed/expected ratio (o/e) 0.78, 90% interval 0.74 to 0.82. Synonymous variants: 781 observed, 661.1 expected, observed/expected ratio (o/e) 1.18, 90% interval 1.11 to 1.25.
Gene-disease validity (ClinGen):
ClinGen rates the evidence that TERT causes each of these diseases.
dyskeratosis congenita, autosomal dominant 2 (semidominant): Definitive. A dyskeratosis congenita that has material basis in an autosomal dominant mutation of TERT on chromosome 5p15.33.
Cancer hallmarks: angiogenesis (promotes); genome instability and mutations (suppresses); invasion and metastasis (promotes); proliferative signalling (promotes); escaping programmed cell death (promotes); cell replicative immortality (promotes)
Homologues: Orthologues: macaque TERT (96% identical), pig TERT (72% identical), dog TERT (72% identical), chimpanzee TERT (67% identical), guinea pig TERT (63% identical), rat Tert (63% identical), mouse Tert (62% identical), tropical clawed frog tert (44% identical), zebrafish tert (32% identical), chimpanzee TERT (31% identical), Caenorhabditis elegans trt-1 (9% identical).
Diseases named in the same sentence as TERT in open-access papers:
TERT is named in the same sentence as 606 diseases in open-access papers, as found by Europe PMC text mining. Sharing a sentence is not in itself a finding about the gene and the disease. The quoted sentences say what the papers report.
glioma (521 papers, 2010 to 2026). A benign or malignant brain and spinal cord tumor that arises from glial cells (astrocytes, oligodendrocytes, ependymal cells). "Key SNPs contributing to risk of childhood glioma included rs59294613 (POT1), rs8105767 (ZNF208), and rs7705526 (TERT), which differed from the top variants previously identified in adult glioma using the same genetic instruments." (PMID 41668119, 2026). "7-T susceptibility-weighted MRI-derived ITSS grade noninvasively predicts histologic grade, Ki-67 labeling index, and telomerase reverse transcriptase (TERT) promoter mutation status in gliomas." (PMID 41925814, 2026). "The 2021 WHO Classification of Central Nervous System Tumors introduces more molecular markers for glioma reclassification, including TERT promoter (TERTp) mutation as a key feature in glioblastoma diagnosis." (PMID 39804195, 2025). "TERT transcription is consistently suppressed in somatic cells, but TERT promoter (TERTp) mutations have been identified in various cancers, including gliomas." (PMID 39804195, 2025). "In this research, we found that gliomas originating from the neocortex have a higher TERT promoter mutation rate and higher TBR values compared to those originating from the mesocortex." (PMID 40149633, 2025). "The role of TERT promoter mutation in the prognosis of patients suffering from glioma in general remains controversial and is nuanced." (PMID 39796751, 2025). "Alleles in the TERC and TERT regions are consistently associated with an increased risk of glioma and longer LTL, such as those at rs1920116 and rs2736100." (PMID 39871386, 2025). "Simultaneously, it recorded AUC values above 0.90 for IDH mutation, 1p/19q co-deletion, and TERT promoter mutation—three molecular biomarkers central to glioma classification and therapeutic decision-making." (PMID 41007223, 2025). "TERT mutations are rare in gastrointestinal and lung cancer but can occur in glioma and thyroid carcinoma." (PMID 40426891, 2025). "The results were consistent with those observed in glioblastomas, showing that gliomas with TERT promoter mutations exhibited higher metabolic activity than TERT wild-type gliomas." (PMID 40149633, 2025). "Mutations in the TERT gene are prevalent in central nervous system tumors, particularly gliomas, with the TERT promoter mutated in 80% of initial cases." (PMID 40514725, 2025). "Tumors carrying TERT promoter mutations demonstrated an increased expression level of TERT compared to wild-type tumors, suggesting a correlation between the mutated promoter and the upregulation of TERT in adult gliomas." (PMID 40362411, 2025). "In our study encompassing all adult‐type gliomas, TERT promoter mutations were observed in 65.1% of patients." (PMID 39804195, 2025). "Comparing the two groups, we found that SLC7A5 (solute carrier family 7 member 5) expression was higher in gliomas with TERT promoter mutations." (PMID 40149633, 2025). "Upon subgroup analysis, we discovered that 77.9% of GBM samples exhibited TERT promoter mutations, with the proportions of C228T and C250T mirroring those observed in the broader adult‐type glioma cohort." (PMID 39804195, 2025). "The frequency of TERT promoter mutations varies among different grades of gliomas, occurring in approximately 45% of grade 2 and grade 3 gliomas and in about 75% of grade 4 glioblastomas." (PMID 39871386, 2025). "Glioma is characterised by low immunogenicity, with only 2% of gliomas having both TERT and IDH mutations, and 7% having only IDH mutations." (PMID 40662483, 2025). "Previous studies have shown that TERT promoter mutations are novel prognostic markers for glioma and can inform potential treatment strategies." (PMID 40463649, 2025). "In this study, TERT promoter mutations were identified in 121 out of 304 glioma patients, accounting for 39.80% of cases." (PMID 39131044, 2024). "The literature suggests a strong correlation between TERT gene polymorphisms and an increased risk of glioma in patients." (PMID 38893240, 2024).
glioma (continued). "All three models demonstrated good predictive performance for the TERT promoter mutation status in low-grade gliomas, with RF showing the best performance (AUC: 0.827)." (PMID 39131044, 2024). "Although this study has made remarkable progress in predicting the mutation status of TERT promoter in glioma, we think this is only the beginning." (PMID 39131044, 2024). "The present risk model will hopefully serve to guide the treatment of gliomas containing mutations in the TERT promoter." (PMID 38499392, 2024). "TERT promoter mutations were identified in 56% (1346/2411) bladder cancers, 43% (966/2243) melanomas, 39% (1403/3614) gliomas, 41% (395/959) thyroid cancers, and 23% (183/782) HNC." (PMID 37462445, 2024). "In gliomas, telomerase is activated mainly by a mutation in the TERT promoter, while ALT activation is usually associated with an ATRX mutation." (PMID 38674026, 2024). "Among the many features in radiomics, T1-weighted enhancement entropy and GLSZM demonstrated significant potential for non-invasive prediction of preoperative TERT promoter mutation status in glioma patients." (PMID 39131044, 2024). "Among patients with lower-grade gliomas (LGGs), those harboring TERT mutations have been found to exhibit a more favorable prognosis than those with wild-type TERT." (PMID 39131044, 2024). "Using the recursive partitioning survival analysis, the combination of IDH and TERT was found to successfully classify gliomas into risk subgroups with significant differences in survival." (PMID 38982347, 2024). "Previous studies have found a positive correlation between TERT promoter mutation status and age at glioma diagnosis." (PMID 39131044, 2024). "The recent WHO update reclassifies all IDH-WT gliomas into glioblastomas based on molecular markers (presence of TERT promoter mutation, EGFR amplification, or chromosome seven gain and ten loss aberrations)." (PMID 38672254, 2024). "TERT is the catalytic subunit of telomerase and mutations in this gene lead to telomerase activation in gliomas." (PMID 38232086, 2024). "Individuals with TERT mutations in gliomas were more likely to develop epilepsy (χ2 = 6.41, P = 0.01) or visual impairment (χ2 = 4.28, P = 0.04) as their onset symptoms." (PMID 38982347, 2024). "TERT promoter mutational status has a prognostic impact in gliomas which is different among the various subtypes of gliomas." (PMID 38240992, 2024). "This indicates that utilizing models constructed from T1C, DWI, and ADC sequences to predict the TERT mutation status in glioma patients is a promising approach." (PMID 39131044, 2024). "These mutations are also associated with increased telomerase activity and TERT upregulation in gliomas." (PMID 38398126, 2024). "Long telomere length and the TERT mutations C228T and C250T are not only indicators of poor survival but also of radioresistance in gliomas." (PMID 38240992, 2024). "The association of TERT mutations with older age and particular onset symptoms like epilepsy or visual impairment hints at a more nuanced understanding of glioma biology." (PMID 38982347, 2024). "Among IDH-mutant gliomas, oligodendrogliomas with 1p/19q codeletion and TERT promoter mutations have the best prognosis, with a median survival of 8 years." (PMID 39595145, 2024). "Although TERT promoter mutations are extremely rare in pediatric gliomas, increased TERC and TERT expression are associated with decreased ΟS in high-grade tumors." (PMID 38240992, 2024). "The 5′UTR of TERT was also recurrently mutated with 5:1295046T > G, which has previously been implicated in glioma and bladder cancer accounting for 23% of mutations within the region." (PMID 39009593, 2024).
glioma (continued). "Telomerase reverse transcriptase (TERT) mutations are prevalent in high-grade gliomas and can be specifically targeted with NRTIs through RNA-dependent RNA polymerase blockade." (PMID 38730705, 2024). "In a separate study, the predictive potential of radiomics features extracted from magnetic resonance spectroscopy was examined to determine the TERT mutation status among 126 patients diagnosed with high‐grade gliomas." (PMID 38798094, 2024). "TERT promoter mutations were more frequent among Asian and Black individuals in bladder cancers and gliomas, but were only increased in Black patients with thyroid cancers." (PMID 38297963, 2024). "By analyzing various quantitative image features extracted from magnetic resonance imaging (MRI) scans using radiomics techniques, researchers have been able to identify potential biomarkers associated with TERT promoter mutations in gliomas." (PMID 38798094, 2024). "Our findings reveal that TERT promoter mutations are frequent events in many cancer types, including bladder cancer, melanoma, thyroid cancer, glioma, and HNC." (PMID 37462445, 2024). "Currently, the primary method for detecting TERT promoter mutations in gliomas involves obtaining tumor tissue through biopsy or surgical resection." (PMID 39131044, 2024). "This study aimed to analyze the radiogenomic features and construct radiogenomic models utilizing medical imaging techniques to predict the TERT promoter mutation status in gliomas." (PMID 39131044, 2024). "Further studies are required to assess the predictive ability of novel functional MRI sequences and quantitative sequences for predicting glioma TERT promoter mutation status." (PMID 39131044, 2024). "(2023) employed a preoperative multiparameter MRI radiomics model to accurately discern IDH‐mutated TERT promoter mutant gliomas." (PMID 38798094, 2024). "Several studies have reported an association between telomerase activation or increased TERT gene expression and the survival outcomes of gliomas." (PMID 39131044, 2024). "Patients with glioma who solely have TERT mutations have poorer prognosis than those who also have IDH mutations and/or 1p/19q codeletion." (PMID 38615034, 2024). "Telomerase reverse transcriptase (TERT) promoter mutation status in gliomas is a key determinant of treatment strategy and prognosis." (PMID 39131044, 2024). "In this study, we investigated the potential of radiomics models, combined with routine MRI sequences (T1C, DWI, and ADC), in predicting the TERT mutation status of glioma patients." (PMID 39131044, 2024). "Previous studies have shown that IDH and TERT double mutations often occur simultaneously with 1p / 19q codeletion in adult gliomas, and such gliomas are classified as oligodendroglioma according to the 2021 version of the CNS classification criteria." (PMID 38982347, 2024). "In the context of gliomas, radiomics studies utilizing multiparameter MRI have demonstrated promising outcomes in predicting TERT promoter mutation status." (PMID 38798094, 2024). "This suggests that the RFE feature selection method performs well in identifying the most relevant features and constructing predictive models, providing a more reliable tool for predicting TERT mutations in glioma patients." (PMID 39131044, 2024). "The automatically trained diagnostic model based on these diverse features exhibited a good ability to predict TERT promoter mutation type in gliomas." (PMID 39131044, 2024). "It is worth noting that mutations in the TERT promoter are linked to the prognosis and treatment resistance in patients with gliomas, indicating their significant impact on disease outcomes and therapeutic response." (PMID 39131044, 2024).